OR4A47 (olfactory receptor family 4 subfamily A member 47)
Description:
Odorant receptor.
Synonyms: OR11-113
Tractability: Antibody: UniProt places it where antibodies can reach, with medium confidence; UniProt predicts a signal peptide or a membrane-spanning region; its Gene Ontology location is reachable by antibodies, with medium confidence.
Gene: Protein-coding gene on chromosome 11 (48,488,793 to 48,489,722, forward strand). Ensembl gene ENSG00000237388.
Subcellular location: Cell membrane
Pathways (Reactome):
Sensory Perception: Expression and translocation of olfactory receptors
Gene Ontology:
Molecular function: olfactory receptor activity; G protein-coupled receptor activity
Biological process: detection of chemical stimulus involved in sensory perception of smell; G protein-coupled receptor signaling pathway
Cellular component: plasma membrane; membrane
Genetic constraint (gnomAD): Loss-of-function variants: 17 observed, 15.63 expected, observed/expected ratio (o/e) 1.09, 90% interval 0.74 to 1.62. The synonymous counts are far from expectation, so gnomAD's model fits this gene poorly and the ratio says little. Missense variants: 437 observed, 334.07 expected, observed/expected ratio (o/e) 1.31, 90% interval 1.21 to 1.42. Synonymous variants: 167 observed, 124.24 expected, observed/expected ratio (o/e) 1.34, 90% interval 1.18 to 1.53.
Homologues: Orthologues: chimpanzee OR4A47 (98% identical), macaque OR4A47 (95% identical), dog OR4A47 (85% identical), dog OR4A47C (83% identical), dog OR4A47D (82% identical), dog OR4A47B (82% identical), rat Or4a47 (81% identical), mouse Or4a47 (80% identical). Paralogues in human: OR4A5 (65% identical), OR4A8 (63% identical), OR4A16 (62% identical), OR4A15 (61% identical), OR4C46 (61% identical), OR4C13 (60% identical), OR4C12 (60% identical), OR4C5 (59% identical), OR4C3 (58% identical), OR4C6 (56% identical), OR4X2 (56% identical), OR4S2 (56% identical), and 116 more.
Diseases named in the same sentence as OR4A47 in open-access papers:
OR4A47 is named in the same sentence as 1 disease in open-access papers, as found by Europe PMC text mining. Sharing a sentence is not in itself a finding about the gene and the disease. The quoted sentences say what the papers report.
cancer (1 paper, 2021). A tumor composed of atypical neoplastic, often pleomorphic cells that invade other tissues. "Using the ChIP Seq bam files, we visualized the exact genomic location of DVL-1 binding (blue peak) at various cancer-associated genes not previously designated as Wnt target genes such as TRIO, COL5A1, EXD3, OR4A47, GLDN, and EFCAB6 compared to IgG control (red peak) using IGV." (PMID 34659647, 2021).